HTR2B (5-hydroxytryptamine receptor 2B)
Diseases named in the same sentence as HTR2B in open-access papers (continued):
Sharing a sentence is not in itself a finding about the gene and the disease.
polyp (1 paper, 2022). A usually exophytic mass attached to the underlying tissue by a broad base or a thin stalk. "After AOM/DSS treatment, the polyp multiplicity and load of Htr2bΔIEC mice were increased compared with those of WT mice, but double knockout of Stat3 and Htr2b attenuated these increases to levels consistent with those of WT mice." (PMID 35664068, 2022).
prostate carcinoma (1 paper, 2024). A carcinoma that arises from epithelial cells of the prostate gland. "Among these, HTR2A and HTR2B were positively associated with lethal prostate cancer, while HTR6 was inversely associated." (PMID 38995644, 2024).
steatosis (1 paper, 2020). Increased lipid within the cytoplasm of cells. "It has also been seen that inhibition of HTR2A and HTR2B reduces proliferation, increases serotonin-induced apoptosis and can attenuate steatosis and fibrosis." (PMID 33081272, 2020).
substance abuse (1 paper, 2023). The use of a drug for a reason other than which it was intended or in a manner or in quantities other than directed. "Collectively, these findings suggest that HTR2B deficits could affect impulsivity and drug-taking behavior, offering one explanation for the common covariation of substance abuse with BP and SCHIZ." (PMID 37031222, 2023). "Therefore, similar to HTR2B, decreased DRD4 might promote the common covariation of substance abuse with BP and SCHIZ." (PMID 37031222, 2023).
tumor (24 papers, 2009 to 2026). "Immunohistochemical result showed that the level of phosphorylated Akt was decreased in Htr2bΔIEC-ER mice, suggesting that 5-HT/5HT2B deficiency may reduce tumor development by inhibiting Akt phosphorylation in the late-stage of CAC." (PMID 35664068, 2022). "In vivo experiments demonstrated that the HTR2B overexpression by lentivirus can suppress tumor growth in vivo." (PMID 40387572, 2025). "To investigate the specific effect of HTR2B activation in macrophage, we examined the single‐cell transcriptomes of immune cells in LM8‐OE‐NC (NC) and LM8‐OE‐HTR2B (OE) tumor tissue." (PMID 40387572, 2025). "The Multiplex Immunofluorescence (mIF) staining of tumor tissues confirmed that overexpression of HTR2B promote the production of Oasl1+macrophage." (PMID 40387572, 2025). "By using cell cultures and xenograft mouse models, recent studies found that inhibition of HTR2B-mediated serotonin signaling suppressed tumor growth in CRC, and that HTR2B facilitated metastasis." (PMID 41034989, 2025). "These CHCs possess features of both tumor cells and macrophages identifiable through their combined expression of tumor-related (gp100+, HTR2B+) or leukocyte-specific proteins (CD45+)." (PMID 38920653, 2024). "For five additional candidate targets including ITGA3 (n = 11), PCDH7 (n = 6), SLC39A10 (n = 6), ATP2B2 (n = 5), and HTR2B (n = 5), a quasi H − score ≥ 150 in at least 5 tumor types was also found." (PMID 33490264, 2021). "HTR2B, which is expressed in untransformed human mammary epithelium, was elevated in carcinomas and was found to increase with tumor stage, and concomitantly was higher in lymph node-positive tumors as compared to node-negative tumors." (PMID 19903352, 2009). "We also observed LUM+/HTR2B + tumor cells close to the mesenchymal component in CRC tissues." (PMID 41034989, 2025). "Interestingly, we observed a dual role of serotonin and HTR2B stimulation under different conditions, and we found shared features of HTR2B + cells with tumor cells expressing NOTCH3." (PMID 41034989, 2025). "In addition, PDAC cells increase the expression of HTR2B compared to normal pancreatic cells, and stimulating HTR2B allows the better survival of tumor cells in unfavorable conditions." (PMID 41034989, 2025). "Previous studies co-agreed that HTR2B regulates invasion and tumor cell migration." (PMID 41034989, 2025). "Interestingly, CDX2 and HTR2B are present in the same tumor samples, showing intratumoral cellular heterogeneity." (PMID 41034989, 2025). "We found that the activation of HTR2B induced migration of tumor cells only in collagen-I." (PMID 41034989, 2025). "The HTR2B antagonist SB204741 impedes tumor growth and enhances prognosis in PDAC." (PMID 38462620, 2024). "We identified UM-associated hybrid cells based on co-expression of melanocytic tumor proteins: Microphthalmia-associated transcription factor (MITF), Tyrosinase (TYR), Melan-A (MLANA), premelanosome protein (PMEL, GP100), 5-hydroxytryptamine receptor 2B (HTR2B) and the pan-leukocyte marker CD45." (PMID 38106024, 2023). "We therefore examined whether the cell passage-dependent reduction in the expression of HTR2B also correlates with similar decreases in the expression of the STAT genes in T142 UM cells when compared to its primary tumor." (PMID 35163491, 2022). "Interestingly in our study, the HTR2B paralog gene HTR2A is substantially expressed in the boundary of the tumour." (PMID 35408449, 2022). "Thus, there is a heterogeneous expression pattern for these markers within the same patient, and the proportion of CDX2 + and HTR2B + tumor cells may greatly influence patient survival." (PMID 41034989, 2025). "We also provide evidence that not only HTR2B, but also NOTCH3 are regulated by mTORC1, HTR2B+/high and NOTCH3+/high CRC cells display overlapping populations with shared common features, and both represent tumor cells with elevated EMT levels." (PMID 41034989, 2025).
tumor (continued). "In this study, we found that CDX2 and HTR2B, markers of the CMS2/3 and CMS4 subgroups, respectively, are present in the same tumor samples." (PMID 41034989, 2025). "In summary, these data provide evidence that HTR2B+/high and NOTCH3+/high CRC cells are overlapping populations with shared common features, and both represent tumor cells with elevated EMT." (PMID 41034989, 2025). "Expression of CDX2 is higher in epithelial-like tumor (CMS2/3), while expression of HTR2B and FRMD6 is higher in mesenchymal-like tumor (CMS4)." (PMID 37404825, 2023). "Among these 5-HTRs, HTR7, HTR2A, HTR2B, and HTR2C were extensively studied in different tumor tissues." (PMID 37795441, 2023). "Thus, we concluded that CDX2 and HTR2B, markers of the CMS2/3 and CMS4 subgroups, respectively, are present in the same tumor samples." (PMID 41034989, 2025). "Immunohistochemical analysis of tissue slides confirmed that HTR2B was absent in the mesenchymal stromal cells but present at a varying level on CRC tumor cells, and it displayed a plasma membrane-bound staining pattern." (PMID 41034989, 2025). "In contrast, tumor cells were heterogeneously positive for CDX2 and HTR2B immunostaining." (PMID 41034989, 2025). "Interestingly, the tumour cells (identified by EpCAM expression) expressed very high levels of the mesenchymal CRC markers ZEB1 and HTR2B, which can be used to distinguish mesenchymal-like CRC (now commonly referred to as CMS4) from non-mesenchymal CRC." (PMID 35296803, 2022). "However, the role of fibroblasts and ECM changes have not been separated from each other, and the tumor cell-specific serotonin receptor HTR2B has not been addressed." (PMID 41034989, 2025). "As inhibition of 5-HT signaling was shown to hinder the growth of a CRC cell line in a xenograft tumor model 25, we sought to examine the impact of inhibition of 5-HT signaling via Htr2b knockout on the tumorigenesis of CAC and determine whether 5-HT acts as a tumor promoter in this disease." (PMID 35664068, 2022).
cancer (17 papers, 2009 to 2025). A tumor composed of atypical neoplastic, often pleomorphic cells that invade other tissues. "This has been demonstrated with a colitis-associated carcinoma mouse model whereby HTR2B knockout increased proliferation in early stages." (PMID 41034989, 2025). "Elevated expression of genes such as ABCC5, LRFN1, ELOVL6, and HTR2B have been associated with metastasis in other cancer types." (PMID 34680307, 2021). "The expression level of HTGPCRs in different tumors showed the specificity of genes and tumors, for example, HTR1B and HTR2B were lowly expressed in most cancers while HTR1D and HTR7 were highly expressed in most cancers." (PMID 39766808, 2024). "In the case of G3 cancer, a decrease in HTR2B expression and the overexpression of HTR1A and HTR1F were also noted." (PMID 34768392, 2021). "Of the genes differentially expressed between two group cancers, HTR2B, CHL1, the ZNF family, YWHAZ and FYN were the most significantly altered." (PMID 24597767, 2014). "We observed that the mTOR pathway, known to be induced in the neighbouring surviving cells around dying cancer cells via a paracrine mechanism in unfavorable conditions, also induced HTR2B expression, providing a link between a nutrient-deprived environment and the higher HTR2B level." (PMID 41034989, 2025). "The regulation of HTR2B in NLRP3 inflammasome pathway in cancer has not been reported in previous studies." (PMID 40387572, 2025). "Our research revealed that HTR1D, HTR2B, and HTR7 were highly expressed in pan-cancer." (PMID 39766808, 2024). "Specifically, HTR2B seemed to be the most upregulated in PCa lines upon exposure to PDK4+ stromal cell-derived CM, validating future efforts to determine whether it accounts for a principal force driving malignant changes of recipient cancer cells." (PMID 37903887, 2023).
metabolic disease (1 paper, 2025). A congenital disorder (due to inherited enzyme abnormality) or acquired (due to failure of a metabolically important organ) disorder resulting from an abnormal metabolic process. "Using a combination of genetic and pharmacological approaches, we aim to elucidate the underlying mechanisms by which Htr2b inhibition modulates skeletal muscle metabolism and to explore its potential as a therapeutic target for alleviating metabolic diseases associated with obesity." (PMID 40451926, 2025). "Our study identifies Htr2b as a novel regulator of skeletal muscle insulin sensitivity and highlighted the therapeutic potential of targeting skeletal muscle 5-HT signaling in the treatment of obesity-related metabolic diseases." (PMID 40451926, 2025).
HTR2B also shares sentences with these, for which no sentence is quoted: Hypertension (4 papers); migraine (4); Parkinson disease (4); schizophrenia (4); Anorexia (3); colorectal cancer (3); gestational diabetes (3); asthma (2); chronic obstructive pulmonary disease (2); colorectal tumor (2); fibrosis (2); melanoma (2); myocardial infarction (2); acute leukemia (1); anxiety disorder (1); aortic valve disease (1); Apathy (1); atherosclerosis (1); autism (1); autoimmune disease (1); Autoimmunity (1); bacterial infections (1); benign ovarian tumors (1); carcinoid syndrome (1); cardiomyopathy (1); cerebrovascular diseases (1); cervical cancer (1); cocaine addiction (1); COVID-19 (1); dysplasia (1).
A further 38 diseases each share a sentence with HTR2B in 1 paper.